IL11 (interleukin 11)
Diseases named in the same sentence as IL11 in open-access papers (continued):
Sharing a sentence is not in itself a finding about the gene and the disease.
infection (45 papers, 2009 to 2025). The state of being infected such as from the introduction of a foreign agent such as serum, vaccine, antigenic substance or organism. "The level of mRNA encoding 4 interleukins (Il10, Il11, Il1rn, Il1a) was increased and 1 interleukin (Il18) decreased in vaginal tissue collected at 35 days post-infection." (PMID 26779389, 2015). "Early study of the proinflammatory response to Chlamydia also indicated that infection also induces production of fibrosis-associated cytokines such as IL-6, IL-11, and IL-17, as well as an extensive portfolio of fibrosis-associated growth factors (e.g. VEGF, CTGF, EGF)." (PMID 37265500, 2023). "Infection-associated induction of known inducers of myofibroblast differentiation (e.g. IL-6, IL-8, IL-11, EGF, and CTGF) may facilitate scarring in a paracrine fashion, by inducing myofibroblast differentiation or by sensitizing tissue-resident fibroblasts to pro-fibrotic stimuli." (PMID 37265500, 2023). "IL-15 and IL-11 are key cytokines reported to take a critical part in the regulation of infection and inflammation." (PMID 36742132, 2023). "In hyper-susceptible I/St mice, B-cell content markedly drops between weeks 12–16 post-infection, paralleled by diffuse lung tissue inflammation and elevated gene expression levels for pro-inflammatory cytokines IL-1, IL-11, IL-17a, and TNF-α." (PMID 36674664, 2023). "As early as 2007, foreign scholars concluded that the application of IL-11 significantly reduced the incidence of infection in patients with AML after chemotherapy." (PMID 37438702, 2023). "These included cytokines and cytokine receptors (Il11, Tnfsf18, and Ackr4), genes involved in infection (Ptgs2 and Heyl), cell adhesion and migration (Spon2 and Mmp10)." (PMID 35293863, 2022). "After infection with Aeromonas hydrophila, we found that the IL-10 and IL-11 expression levels were upregulated in each group, while TLR-4, MYD88, and TNF-α were down regulated." (PMID 36139830, 2022). "In several models of inflammation and infection, IL-11 was identified to be an immunomodulatory cytokine as it inhibits the release of pro-inflammatory cytokines." (PMID 33334075, 2020). "We have previously shown that IL-11 mRNA is significantly but modestly induced in the lung during E. coli pneumonia after 24 hours of infection." (PMID 31415618, 2019). "Treatment with a neutralizing IL-11 antibody at the time of infection significantly decreased BALF IL-11 protein detection." (PMID 31415618, 2019). "In contrast to our findings in lung tissue, levels of IL-11 protein in BALF decreased after 6h of infection, recovering to baseline levels by 48h." (PMID 31415618, 2019). "The DEGs involved in cytokine signaling were also up-regulated following infection with EV-F7, and included IL-6, IL-11, leukemia inhibitory factor (LIF), granulocyte-macrophage colony-stimulating (GM-CSF), and colony stimulating factor 2 (CSF2)." (PMID 30545363, 2018). "After LPS, poly I:C or pathogen infection, Japanese flounder, rainbow trout and gibel carp IL11 also increased expression after challenge with viral." (PMID 28738780, 2017). "Viral and bacterial infection or stimulation by cytokines such as Interleukin-1, Tumor Necrosis Factor-α, and Transforming Growth Factor-β1 induce interleukin-11 expression in mouse dendritic cells, macrophages, and other tissues." (PMID 25775398, 2015). "Intriguingly, IL-6 and IL-11 transcripts were up-regulated over 30-fold correlating positively with both infection readouts." (PMID 23865616, 2013). "A wide range of cytokines, such as IL-3, IL-11, and granulocyte–macrophage colony-stimulating factors, as well as thrombopoietin and IL-6, are involved in stimulating platelet production in response to infection." (PMID 40427060, 2025). "Moreover, the 11 cytokines (i.e., SDF-1, SCYB16, sCD30, IL-11, IL-18, IL-8, IFN-γ, TNF-α, sTNF-R2, M-CSF, and I-309) were associated with the infection, mortality, disease progression and recovery, and long-term hospitalization." (PMID 38476443, 2024).
infection (continued). "Given the downregulation of Il11ra1 during infection, it will be interesting to investigate whether enhanced expression of IL-11 and its related cytokines promote tissue repair." (PMID 36417363, 2022). "Infection of fibroblasts induced IL-11 secretion, which increased after RhoA depletion and may play a role in host cell survival." (PMID 33824207, 2021). "Moreover, IL-11 is also involved in the recruitment of neutrophils to sites of inflammation or infection." (PMID 33334075, 2020). "Interestingly, we were able to confirm our results regarding the STAT3 pathway involvement during BKPyV infection and we identified IL‐11 as interesting therapeutic target, since it was significantly elevated during infection." (PMID 32588533, 2020). "Interestingly, the results of IL‐11 were significant from day 6 following infection onwards (day 3 P = 0.073; day 6 P = 0.045; day 9 P = 0.026)." (PMID 32588533, 2020). "The gp130 cytokines IL-6, IL-11 and IL-27 differentially affect the outcome of infection with Mtb." (PMID 33334075, 2020). "Many IL-11 accumulate in cells at 48 h post-infection (hpi), which implies that the release of mature IL-11 may be influenced by PEDV infection." (PMID 31864417, 2019). "We began by establishing how IL-11 changes temporally during infection." (PMID 31415618, 2019). "Overall, we conclude that maintenance of lung IL-11 concentrations may influence acute pulmonary inflammation during infection, albeit modestly." (PMID 31415618, 2019). "Infection of PNEs with RV-A16 at MOI 0.01 or MOI 1 for 24 h resulted in the upregulation (> twofold) of 6 cytokines (IL-1β, IL-1α, IFN-γ, I-309, TNF-α and IL-11)." (PMID 40916026, 2025). "IL-11 activation was VFRA-specific, being upregulated in infections by Tulahuen strain, which belongs to the DTU VI as VFRA, suggesting that IL-11 activation would be DTU-specific." (PMID 39000601, 2024). "As the infection of HBV in vitro (HepAD38 and HepG2) as well as in vivo resulted in reduced expression of IL-15 and IL-11, we further checked if the treatment of immune modulators can elevate the expression of both cytokines." (PMID 36742132, 2023). "The differentially expressed cytokines such as IL6, IL10, IL11, IL15, TNFSF10, TNFRSF6B and TNFAIP6 were detected in the lung of goats after Pm infection in this study." (PMID 35739866, 2022). "Infection with SARS-CoV-2 and several influenza viruses can lead to alterations in CSF2 and IL-11 expressions." (PMID 36093436, 2022). "It was found that IL-1β1, IL-8, IL-11, TNF-α2, COX-2, the acute phase protein serum amyloid A, C-type lectins CD209a and CD209b were all upregulated during infection." (PMID 25088077, 2014). "In the Jak-STAT signalling pathway 12.4% of the genes were differentially expressed at the beginning of infection, including greatly increased expression (>10 fold) of IL6, IL7R, IL11 and IL20." (PMID 23326599, 2013). "Vaccination did not affect IL-11 mRNA levels, but downregulated the constitutive mRNA levels of Il11ra1, which remained downregulated during the first 4 days of infection." (PMID 40243929, 2025). "Finally, expression of interleukins in general and CXCL12 specifically demonstrated infection and PM-specific patterns characterized by unique upregulation of IL24 following Winter PM and IL11 and CXCL12 upregulation following Spring PM co-exposure." (PMID 40671793, 2025). "Furthermore, in all the VFRA infections, independently of SLAMF1 expression, we had an upregulation of the IL-11 pathway." (PMID 39000601, 2024). "On Day 0 (day of infection), we were not able to detect IL‐6 or IL‐11 in the supernatants of all 3D cultures (infection and negative control)." (PMID 32588533, 2020). "Neutralization of IL-11 decreased neutrophil recruitment, but did not alter airspace macrophage numbers following 24h of infection." (PMID 31415618, 2019).
infection (continued). "In agreement with the transcriptomic data, several cytokines (e.g. IL-11 and IL-22) were found to increase upon infection, but no strong difference was observed between wildtype and ΔcnfY mutant-infected animals." (PMID 29390040, 2018). "The hematologic toxicities were generally mild, never exceeding grade 3, and reversible after introduction of stimulating agents like G-CSF and IL-11, without obvious infection or bleeding symptoms developed." (PMID 27659525, 2016). "Of note, the level of IL-11 was significantly higher in infection involving a disseminating serovar relative to a non-disseminating variant." (PMID 27367858, 2016). "Finally, we evaluated the effect of IL-11 neutralization in the absence of infection, and did not see a significant difference in BALF protein." (PMID 31415618, 2019). "Finally, neutralization of IL-11 in the absence of infection had no impact on alveolar cellularity." (PMID 31415618, 2019).
cardiovascular disease (9 papers, 2019 to 2025). "The scRNA-seq experiment conducted in a fibrosis-susceptible mouse model identified a subset of IL-11-positive fibroblasts, indicating that IL-11 plays an important role in fibroblast differentiation into myofibroblasts in cardiovascular diseases." (PMID 39452092, 2024). "Interleukin-11 (IL-11) is an important inflammatory cytokine and has been demonstrated to participate in cardiovascular diseases." (PMID 30728748, 2019). "The previous evidence suggested that IL-11 plays an important role in cardiovascular diseases." (PMID 30728748, 2019). "This discovery of IL-11 role in a specific fibroblast-subpopulation during differentiation and activation has supported the notion that targeting IL-11 could be a multi-faceted approach to cardiovascular disease." (PMID 31921894, 2019).
kidney disease (8 papers, 2022 to 2024). "Excess of IL-11 is thought to be the cause of the cardiorenal syndrome, in which kidney disease causes heart disease and vice versa, as IL-11 contributes to both kidney and cardiac fibrosis." (PMID 38732588, 2024). "Our findings of IL11-associated EMT/EndMT are in line with recent studies of kidney disease, where IL11 causes pathogenic EMT." (PMID 37629170, 2023). "In renal disease, the feedforward production of IL-11 in pTECs is held responsible for the transition to CKD." (PMID 38732588, 2024). "These pathologies were collectively mitigated by anti–IL-11 therapy, thus further confirming the mechanistic importance of IL-11 in renal disease." (PMID 37816442, 2023). "Recent studies have shown IL11 to be pro-fibrotic, pro-inflammatory and anti-regenerative in heart, liver, lung and kidney disease in mice and humans." (PMID 36629985, 2023). "The potential of IL11 as a therapeutic target in kidney disease was subsequently demonstrated in two publications in 2022." (PMID 38054591, 2023). "Taken as a whole, it is apparent that the earlier literature pointed to a possible role of IL-11 in renal disease, a notion that has now been established through a range of in vitro and in vivo models." (PMID 37816442, 2023). "This likely explains the large effect of IL-11 inhibition in kidney disease as it addresses at least two cellular components of disease pathology: the stroma and the epithelium." (PMID 37816442, 2023). "Here we hypothesized that IL11, which activates ERK signaling required for EMT9,10,20, may cause TEC mesenchymal transition and dysfunction as an initiating pathology in kidney disease." (PMID 36470928, 2022). "Furthermore, anti-IL-11 treatment reverses kidney disease in a mouse model of CKD." (PMID 38732588, 2024). "In the kidney, there remains an outstanding question pertaining to the effects of IL-11 on inflammatory cells: although inhibition of IL-11 signaling clearly reduces kidney inflammation in renal disease, it is not known whether this effect is a direct or indirect consequence of IL-11 action." (PMID 37816442, 2023).
heart disease (7 papers, 2017 to 2024). "Interleukin (IL)-11 is regulated in various heart diseases and has recently been reported to be an important cytokine in fibrosis in this organ." (PMID 38392279, 2024). "In this review, the pathophysiological effects of interleukins including the IL-1 family (IL-1, IL-18, IL-33, and IL-37), IL-2, IL-4, the IL-6 family (IL-6 and IL-11), IL-8, IL-10, and IL-17 on primary cell types of heart disease is elucidated." (PMID 37047468, 2023). "This review will primarily focus on the pathophysiological effects of various interleukins including the IL-1 family (IL-1, IL-18, IL-33, IL-37), IL-2, IL-4, the IL-6 family (IL-6 and IL-11), IL-8, IL-10, IL-17 on primary cells of heart disease-CMs, FBs, ECs, and immune cells." (PMID 37047468, 2023). "This evidence demonstrates the therapeutic role of IL-11 in heart disease." (PMID 37047468, 2023). "Inhibiting interleukin 11 could possibly be an effective treatment against several forms of heart diseases and our model could potentially be used for such investigations (Fernández-Ruiz, 2018)." (PMID 32878883, 2020). "The plasma concentrations of IL-11 were measured in 240 patients with chronic HF (CHF) and 80 control subjects without signs of significant heart disease." (PMID 30728748, 2019).
gastrointestinal tumor (3 papers, 2019 to 2025). "This gastrointestinal tumor progression is driven by upregulating epiregulin (EREG) and interleukin-11 (IL-11) and chemotherapy resistance." (PMID 40497943, 2025). "Of note, EGFP+ cells only appeared in the colon tumors of ApcMin/+;Il11-Egfp reporter mice, but not ApcMin/+ mice, indicating that EGFP signals in ApcMin/+;Il11-Egfp reporter mice did not likely reflect the autofluorescence, but represented specific signals of IL-11." (PMID 33863879, 2021).
degenerative diseases (2 papers, 2023 to 2024). "Genetic and pharmacological IL11 blockade reduces inflammaging, improving healthspan, lifespan, and longevity in male and female mice, highlighting IL11 as a new inflammatory aging clock and a potential molecular target in inflammaging‐associated human degenerative diseases." (PMID 39361945, 2024).
bacterial infection (1 paper, 2023). "In the lung, early studies showed up-regulation of IL11 following viral or bacterial infection, and in asthma." (PMID 38054591, 2023). "However, following viral or bacterial infection, Il11 levels are elevated systemically." (PMID 38054591, 2023).
genetic diseases (1 paper, 2023). "It is interesting to note that IL11 is important for the pathobiology of some rare human genetic diseases where it is up-regulated due to a shared molecular cue or activated because of a generic cellular stress." (PMID 38054591, 2023).
hematological malignancies (1 paper, 2014). "IL-11, an important mediator of hematopoiesis, has been investigated as an experimental treatment for hematological malignancies." (PMID 24922518, 2014).
hematopoietic cancers (1 paper, 2019). "In non-hematopoietic cancers, protection of MKPs against chemotherapy-induced cytotoxicity via the administration of hematopoietic cytokines (Stem Cell Factor [SCF], Interleukin 11 [IL-11] and thrombopoietin receptor agonists) has been previously proposed." (PMID 30808933, 2019).
IL11 also shares sentences with these, for which no sentence is quoted: non-small cell lung carcinoma (5 papers); chronic periodontitis (4); esophageal squamous cell carcinoma (3); Hepatic steatosis (3); multiple myeloma (3); acute myocardial infarction (2); Chronic Myelogenous Leukemia (2); Encephalopathy (2); inflammation (2); intracerebral hemorrhage (2); osteosclerosis (2); plasmacytoma (2); acute pancreatitis (1); agranulocytosis (1); albinism (1); alcohol cirrhosis (1); alcoholic liver diseases (1); alcoholic steatohepatitis (1); allergic asthma (1); Anxiety (1); anxiety disorder (1); aortic stenosis (1); arterial disease (1); atopic dermatitis (1); Azoospermia (1); basal cell carcinoma (1); bone disorder (1); brain disorder (1); brain injury (1); capillary leak syndrome (1).
A further 67 diseases each share a sentence with IL11 in 1 paper.